H1-9P (H1.9 linker histone, pseudogene)
Description:
DNA-binding protein that may be implicated in chromatin remodeling and/or transcriptional regulation during spermiogenesis, the process of spermatid maturation into spermatozoa.
Synonyms: H1.9; formerly HILS1; H1-9
Gene: Transcribed unitary pseudogene on chromosome 17 (50,171,514 to 50,171,936, reverse strand). Ensembl gene ENSG00000188662.
Subcellular location: Nucleus; Chromosome